DKC1 (dyskerin pseudouridine synthase 1)
Diseases named in the same sentence as DKC1 in open-access papers (continued):
Sharing a sentence is not in itself a finding about the gene and the disease.
breast carcinoma (21 papers, 2009 to 2025). "In breast cancer cell lines, the downregulation of DKC1 was found to be related to reduced global rRNA pseudouridylation while in breast carcinomas DKC1 expression is strictly associated with survival." (PMID 37260601, 2023). "DKC1 is associated with several cancers such as colorectal cancer, glioblastoma, prostate cancer, breast cancer, lung adenocarcinoma." (PMID 37925171, 2023). "For example, DKC1 expression levels, the pseudouridylation of rRNA, and reduced telomere length are associated with a better prognosis in breast cancer." (PMID 36360287, 2022). "Low expression of DKC1, rRNA pseudouridine modification, and decreased intrinsic ribosomal activity are associated with better breast cancer prognosis." (PMID 35721510, 2022). "In a recent study in breast cancer, DKC1 over-expression associated with unfavourable clinicopathological characteristics and poor outcome." (PMID 33450922, 2021). "In contrast, high DKC1 expression levels were linked to poor DMFS, OS, PPS, and RFS prognosis for breast cancer." (PMID 38082360, 2023). "The correlation between DKC1 expression levels and survival in various cancers, including gastric cancer, liver cancer, ovarian cancer, lung cancer and breast cancer, was assessed using the KM plotter." (PMID 38082360, 2023). "Studies have shown that DKC1 is dysregulated in a variety of tumors, including glioma, breast cancer, and nonsmall cell lung cancer, but it is less well-studied in neuroblastoma." (PMID 37426487, 2023). "For instance, the overexpression of Dyskerin pseudouridine synthase 1 (DKC1) was shown to be significantly correlated with unfavourable clinicopathological parameters and poor prognosis of breast cancer." (PMID 36457503, 2022). "Two publicly available “Breast Cancer Gene-Expression Miner v4.3” and TCGA breast cancer datasets revealed high DKC1 mRNA levels to significantly correlate with larger tumour size, higher tumour grades, and poor prognosis." (PMID 33450922, 2021). "For example, in breast cancer, decreased levels of DKC1 expression, rRNA pseudouridylation and telomere length correlate with better prognosis." (PMID 33461542, 2021). "In a previous study, we presented follow-up data from 62 patients with primary breast carcinoma in which patients with tumors expressing high DKC1 mRNA levels were characterized by a worse prognosis than patients with intermediate or low levels." (PMID 33255756, 2020). "DKC1 expression was assessed using mRNA data of Molecular Taxonomy of Breast Cancer International Consortium (METABRIC, n = 1980) and TCGA (n = 855)." (PMID 32868896, 2020). "In breast cancer tissue, when DKC1 mRNA levels were very low, TA was significantly decreased, independently of the level of hTERT expression." (PMID 33317189, 2020). "The defect in the protein synthesis described in cells originated from X-DC patients and DKC1 hypomorphic mice has also been observed in a sub-set of human breast carcinomas characterized by a strong reduction in DKC1 expression and function." (PMID 23821664, 2013). "It remains to be demonstrated that the increased levels of DKC1 mRNA in prostate cancer tissues result in an overexpression of the protein, as was shown for breast cancer." (PMID 19755982, 2009). "In keeping with this interpretation, in breast cancer cells, a close correlation between pseudouridine levels and DKC1 expression has been directly demonstrated." (PMID 19755982, 2009). "Additionally, in vitro DKC1 gene knock-down using siRNA in MCF-7 breast cancer cells, reduced TA via a reduction in hTERC levels." (PMID 33317189, 2020).
breast carcinoma (continued). "In addition, to provide functional insights into the relevance of increased VEGF-IRES–mediated translation on DKC1 KD in breast cancer cells, we assessed how the clonogenic potential of breast cancer cell lines is modified by DKC1 KD." (PMID 23821664, 2013). "In the DKC1 hypomorphic mouse, a partial lack of dyskerin function is associated with the increased development of different tumor types, including breast carcinomas." (PMID 23821664, 2013). "DKC1 and PUS7 have been proven to be oncogenes in many cancers, such as colorectal cancer, glioblastoma, prostate cancer, breast cancer and lung adenocarcinoma." (PMID 37925171, 2023). "The effect of dyskerin depletion on the polysomal recruitment of these snoRTs was further validated by RT-qPCR using different siRNA sequences to reduce DKC1 levels in MCF7 and also MDA-MB-231 breast cancer cells." (PMID 35996163, 2022). "Another study reported a similar connection between the elevated expression of DKC1 with upregulated expression of SNORA67 and increased U1445 modification on 18S ribosomal RNA in a breast cancer cell line." (PMID 35719370, 2022). "Similarly, in breast cancer high MRE11 expression was associated with a more malignant behavior of the disease, lymph node metastasis, and higher recurrence rates after radiotherapy and chemotherapy, whereas low DKC1 expression and activity were related to a better prognosis." (PMID 26366868, 2015). "Firstly, we transiently reduced DKC1 mRNA levels by specific siRNA transfection in MCF7 and MDA-MB 231 breast cancer cell lines." (PMID 23821664, 2013). "Additionally, DKC1 overexpression enhances ribosomal activity by upregulating SNORA67, promoting the early malignant transformation of breast cancer cells." (PMID 41301542, 2025). "DKC1 also has similar manifestations in breast cancer, nonsmall cell lung cancer, and colorectal cancer." (PMID 37426487, 2023). "Three inhibitors were developed based on the interaction between DKC1 and TERC to inhibit telomerase activity in breast cancer cell lines, which may aid in development of pseudouridine synthase inhibitors for treatment of cancer." (PMID 35721510, 2022). "However, to overcome the issue, 20 full face sections of randomly selected breast cancer cases were stained, prior to TMA application, with DKC1 antibody to assess the staining homogeneity and to evaluate the pertinence of using tissue microarrays (TMAs)." (PMID 32868896, 2020). "DKC1 KD significantly increased the ratio between the activities of two reporters of a bicistronic construct containing the VEGF-IRES in both MCF7 and MDA-MB231 breast cancer cells." (PMID 23821664, 2013).
glioma (19 papers, 2020 to 2026). A benign or malignant brain and spinal cord tumor that arises from glial cells (astrocytes, oligodendrocytes, ependymal cells). "DKC1 has been linked to malignant proliferation and invasion in prostate cancer, glioma, and CRC." (PMID 40260225, 2025). "DKC1 expression was elevated in glioma tissues and was linked to the WHO stages of tumors." (PMID 37612540, 2023). "DKC1 alterations have been found associated to skin cancer, breast, colon, lung, prostate, head and neck, glioma, HCCs, and specially bone marrow failure syndromes and hematologic malignancies including chronic lymphocytic leukaemia or multiple myeloma." (PMID 33461542, 2021). "For example, in glioma, increased DKC1 expression promotes glioma progression by inducing glioma cell growth and migration." (PMID 38572667, 2024). "Studies have shown that the expression of DKC1 is significantly increased in the pathological tissue of glioma, and the expression of DKC1 is related to the tumor stage of glioma." (PMID 37426487, 2023). "In clear cell renal cell carcinoma (ccRCC), glioma, NB, and liver cancer, DKC1 expression is up-regulated and promotes tumor progression, but it can also act as a tumor suppressor." (PMID 36770809, 2023). "Knockdown of DKC1 significantly inhibited glioma cell growth and motility, possibly by inhibiting the expression of N-cadherin, HIF-1α, and MMP2." (PMID 37612540, 2023). "Consistent with previous findings, elevated expression of DKC1 in glioma cell lines was also identified." (PMID 36142793, 2022). "In gliomas, the high expression of DKC1 stimulates the increased expression of glioma growth regulators to promote glioma cell migration and progression." (PMID 36360287, 2022). "The expression levels of RPUSD1 and DKC1 in high-grade gliomas were higher than that in low-grade gliomas." (PMID 35118063, 2021). "The results showed that PUS1, PUS7, and DKC1 were significantly correlated with the prognosis of gliomas in different subgroups." (PMID 35118063, 2021). "DKC1 is deregulated in glioma and knockdown of DKC1 restrain cancer cell proliferation, invasion and migration." (PMID 32071816, 2020). "DKC1 downregulation can also inhibit the growth of glioma cells by altering the expression of cell cycle-related molecules, causing cells to arrest in G1 phase." (PMID 32528520, 2020). "One of the ψ writers, DKC1, is significantly upregulated in glioma and correlates with the WHO stages of tumors." (PMID 32244981, 2020). "DKC1 promotes glioma cell growth by stimulating cell cycle progression and activates migration via upregulating N-cadherin, hypoxia inducible factor 1 subunit α (HIF1A), and MMP-2 expression." (PMID 32244981, 2020). "Upregulation of DKC1 in gliomas is common and necessary for extensive tumor growth." (PMID 37426487, 2023). "Further investigations into the specific mechanisms by which DKC1 influences glioma pathogenesis could shed light on potential therapeutic targets for glioma treatment." (PMID 37593751, 2023). "By understanding the involvement of DKC1 and HNRNPU in the context of glioma biology, researchers may gain valuable insights into the underlying mechanisms of glioma pathogenesis." (PMID 37593751, 2023). "In glioma, DKC1 up-regulation was common and necessary for extensive tumor growth." (PMID 36437949, 2022). "Lastly, concerning snRNAs and snoRNAs, it has been shown that pseudouridine synthetases may be involved in glioma development, with dyskerin pseudouridine synthase 1 (DKC1) being upregulated in gliomas and correlating with WHO grade." (PMID 35681635, 2022). "Glioma is one of several human cancers in which DKC1 is upregulated." (PMID 36142793, 2022). "Additionally, downregulation of DKC1 inhibited prostate cancer cell growth and glioma cell invasion." (PMID 36457503, 2022).
glioma (continued). "In glioma, increased expression of DKC1 and pseudouridylation promote glioma cell growth and migration by inducing the upregulated expression of gliomagenesis regulators, although the direct role of increased pseudouridylation of RNAs and gliomagenesis remains unexplored." (PMID 33461542, 2021). "In vitro experiments also confirmed that glioma cells with DKC1 knockout showed low activity." (PMID 32528520, 2020). "This suggests that DKC1 may play a vital role in glioma development and progression." (PMID 37593751, 2023). "DKC1 could upregulate the expression of N-cadherin, MMP-2, HIF1A, CDK2, and cyclin E, and the glioma cells with DKC1 knockdown exhibited low motility." (PMID 36437949, 2022).
prostate carcinoma (17 papers, 2009 to 2025). A carcinoma that arises from epithelial cells of the prostate gland. "Our data indicate that DKC1 overexpression is common in prostate cancer, and is associated with adverse histopathological features, especially tumour extension." (PMID 19755982, 2009). "Moreover, in view of the association of increased DKC1 mRNA with prostate cancer stage and a tendency towards association with recurrence, it seems highly desirable to explore the prognostic value of dyskerin expression using tissue microarrays." (PMID 19755982, 2009). "Dyskerin(DKC1), a core-component of the telomerase holoenzyme is typically overexpressed in breast and prostate cancers, whereas its expression is often reduced in endometrial carcinoma and pituitary tumors." (PMID 39871386, 2025). "The upregulation of DKC1 is closely related to poor prognosis in prostate cancer, neuroblastoma, and hepatocellular carcinoma." (PMID 36319976, 2022). "High expression of TERC, DKC1 and high levels of Ψ on telomerase RNA correlate with poor prognosis and malignant progression of lung and prostate cancer." (PMID 33564819, 2021). "The transformation of prostate cancer cells with a DKC1 small interfering RNA resulted in complete cessation of cell growth and proliferation after at most three passages, corresponding to ten days of treatment." (PMID 22912812, 2012). "Treatment of 22Rv1 and Du145 prostate carcinoma cell lines with either one of three previously published DKC1 siRNAs for 3 days diminished DKC1 mRNA levels by 90–95% compared with cells treated with a control siRNA." (PMID 19755982, 2009). "As the DKC1 gene is located at Xq28 and gain of X-chromosome sequences is often observed in advanced stage prostate cancers, the gene copy number was investigated by quantitative PCR in 45 cancer specimens." (PMID 19755982, 2009). "Expression of DKC1 was measured by quantitative RT–PCR in prostate cancer tissues in relation to hTR and the proliferation marker MKI67." (PMID 19755982, 2009). "DKC1 upregulation in prostate cancers is common and likely to be necessary for extensive tumour growth." (PMID 19755982, 2009). "Expression of DKC1 was first studied by real-time RT–PCR in a series of 47 M0 prostate carcinomas and 13 benign prostate tissues from prostatectomies." (PMID 19755982, 2009). "To investigate possible functional consequences of DKC1 overexpression, we used a siRNA-based approach in prostate cancer cell lines." (PMID 19755982, 2009). "Other studies showed that DKC1 can be overexpressed in lung and prostate cancer." (PMID 33564819, 2021). "Moreover, DKC1 knockdown by siRNA treatment in prostate cancer cells affected cell proliferation but also resulted in decreased cell size and spontaneous detachment, compatible with a defect in protein biosynthesis." (PMID 26366868, 2015). "In this study, we report DKC1 overexpression in prostate cancers." (PMID 19755982, 2009). "Thus, differential levels of DKC1 mRNA in prostate cancer tissues are related to differences in cell proliferation, but not closely so." (PMID 19755982, 2009). "This prompted us to investigate DKC1 expression and dyskerin function in prostate cancer." (PMID 19755982, 2009). "Increased levels of DKC1 and H/ACA snoRNA together with elevated levels of pseudouridine were reported in vitro studies conducted on prostate cancer cells." (PMID 35719370, 2022). "First, Ψ can function as a biomarker for prostate cancer because certain nucleolar RNAs (H/ACA snoRNAs) and the dyskerin (DKC1) protein can upregulate the transformation of U to Ψ and contribute to the advancement to cancer." (PMID 32303268, 2020). "In prostate cancer tissues, a moderate and significant correlation has been observed between DKC1 and MKI67 mRNA levels, but not with PCNA mRNA." (PMID 22912812, 2012). "As we did not observe increased gene copy numbers in prostate cancers with DKC1 overexpression, they are likely epigenetic." (PMID 19755982, 2009).
prostate carcinoma (continued). "Thus, in primary prostate cancers, gain of Xq28 does not seem to represent a major factor responsible for DKC1 overexpression." (PMID 19755982, 2009). "In this respect, it could be significant that DKC1 was recently identified as a direct target of MYC, a major regulator of cancer cell growth frequently overexpressed in aggressive breast and prostate cancers." (PMID 19755982, 2009).
X-linked dyskeratosis congenita (17 papers, 2010 to 2025). "XL-HHS and the "classical" X-linked dyskeratosis congenita (XL-DC) affect only males and are due to mutations of the DKC1 gene within Xq28, encoding dyskerin, a component of telomerase." (PMID 21078154, 2010).
colorectal cancer (16 papers, 2019 to 2026). A primary or metastatic malignant neoplasm that affects the colon or rectum. "A recent study found that DKC1 was a potential therapeutic target in colorectal cancer, and its increased expression was associated with poor prognosis." (PMID 36437949, 2022). "For example, in contrast to our results on ECs, reports on prostate, hepatocellular carcinoma, and colorectal cancers showed that high DKC1 is commonly associated with an extensive tumour growth pattern." (PMID 33450922, 2021). "Moreover, higher expression of DKC1 in colorectal cancer is associated with poorer prognosis, which suggests that DKC1 is a candidate therapeutic target for CRC." (PMID 34026451, 2021). "DKC1 might be involved in predisposition to colorectal cancer in young adulthood; therefore, appropriate surveillance may be considered." (PMID 31027506, 2019). "In colorectal cancer, DKC1 is an important regulator affecting colorectal cancer cell proliferation." (PMID 38572667, 2024). "In colorectal cancer, concurrent use of the DKC1 inhibitor pyrazofurin and trametinib can effectively suppress tumor growth." (PMID 38082360, 2023). "Via genome-wide shRNA screening, Guangyuan Kan and his colleagues identified DKC1 as a molecular driver in colorectal cancer progression and they then proved the therapeutic efficiency of synergistic inhibition of DKC1 and MEK1/2 in fighting tumor." (PMID 37188742, 2023). "High expression levels of DKC1 promoted colorectal cancer progression by increasing the expression of ribosomal proteins in a pseudouridine synthase activity‐dependent manner." (PMID 34026451, 2021). "qRT‐PCR analysis of 18 pairs of human primary colorectal cancer tissues and adjacent normal tissues showed higher expression of DKC1 mRNA in cancerous tissues." (PMID 34026451, 2021). "In summary, we identified DKC1 as an essential gene for colorectal cancer cell proliferation through genome‐wide RNAi screening." (PMID 34026451, 2021). "Colorectal cancer patients with higher DKC1 expression has consistently poorer overall survival and progression‐free survival outcomes." (PMID 34026451, 2021). "For instance, DKC1 stabilizes the mRNA of some ribosomal proteins depending on its pseudouridine synthase activity, thereby promoting colorectal cancer progression in vitro and in vivo." (PMID 35118063, 2021). "DKC1 binds to and stabilizes the mRNA of some ribosomal proteins in a manner dependent on its pseudouridine synthase activity, thus promoting colorectal cancer progression in vitro and in vivo." (PMID 34026451, 2021). "Taken together, these data suggest that DKC1 is an essential gene and candidate therapeutic target for colorectal cancer." (PMID 34026451, 2021). "Away from its role on telomeres, DKC1 has been shown to bind HIF1α promoter and increases the expression of HIF1α in colorectal cancer (CRC)." (PMID 33599797, 2021). "Dyskerin pseudouridine synthase 1 (DKC1), screened using the genome‐wide RNAi strategy, is a previously unidentified key regulator that promotes colorectal cancer cell proliferation." (PMID 34026451, 2021). "The study identified Dyskerin pseudouridine synthase 1 (DKC1) is upregulated in colorectal cancer and stabilizes the mRNA of several ribosomal proteins (RPs) to promote cancer progression." (PMID 34026451, 2021). "In this study, we identified DKC1 as an essential top‐scoring gene in colorectal cancer via genome‐wide shRNA screening." (PMID 34026451, 2021). "This work indicates that DKC1 is a candidate therapeutic target in colorectal cancer." (PMID 34026451, 2021). "As DKC1 accelerated colorectal cancer cell growth, we further explored whether this function is mediated by DKC1‐targeted ribosomal proteins." (PMID 34026451, 2021). "In addition, DKC1 knockdown significantly reduced human colorectal cancer (hCRC) organoid number and size." (PMID 34026451, 2021). "Furthermore, DKC1 is markedly upregulated in colorectal cancer tissues compared to adjacent normal tissues." (PMID 34026451, 2021).